HGF (hepatocyte growth factor)
Diseases named in the same sentence as HGF in open-access papers (continued):
Sharing a sentence is not in itself a finding about the gene and the disease.
tumor (continued). "Next, to dissect the mechanism of how ERβ can increase the HUVEC tube formation, we focused on tumor angiogenesis-related genes, including Angiogenin, ANGPT-2, bFGF, EGF, HB-EGF, HGF, Leptin, PLGF, and VEGF-A35." (PMID 32409702, 2020). "Thus, HGF/c-Met axis might be of high interest in regulating tumor progression in HCC." (PMID 32083078, 2020). "MDSCs promote tumor epithelial–mesenchymal transformation (EMT) by expressing factors, such as TGFβ, IL-6, hepatocyte growth factor (HGF), and high mobility group binding (HMGB)-1, which makes tumors exhibit aggressive phenotypes with high migration ability." (PMID 32942545, 2020). "Inhibition of SF/HGF and c-met expression anti-SF and anti-c-MET U1/ribozymes promotes tumor cell apoptosis and inhibits tumor angiogenesis in an in vivo glioma model." (PMID 32152825, 2020). "The HGF/c-MET axis plays a key role in many stages of the metastatic process, from cellular dissociation in the primary tumour to reassociation within metastatic sites." (PMID 33271944, 2020). "The biological activities that are driven by the HGF-MET pathway all play a role in the acquisition of malignant characteristics by tumor cells, namely, invasion, metastasis, and drug resistance in the tumor microenvironment." (PMID 33121208, 2020). "Tumour growth is fuelled by the SASP, and specifically by the secretion of the hepatocyte growth factor (HGF)." (PMID 32708331, 2020). "Signaling events mediated by estrogen receptor, hepatocyte growth factor (HGF) and platelet-derived growth factor (PDGF) receptors, all known to drive tumor growth, were also enriched." (PMID 32575471, 2020). "The critical role of HGF/c-MET pathway in exerting mitogenic and motogenic effects on tumour cells has been reported in several cancers." (PMID 33271944, 2020). "The interaction between the HGF/c-MET pathway and anti-tumour immune-response is complex and yet to be fully understood." (PMID 33396187, 2020). "Recently, a robust EndMT induced by HGF/c-Met was described in GBM, resulting in aberrant vasculature and in an increase of tumor cells chemoresistant to temozolomide, undoubtedly linked to drug delivery failure and hypoxia." (PMID 32923440, 2020). "When both neutralizing antibodies to IL-6 and HGF were simultaneously added to the CAF-CM, the invasive ability of tumor cells was most strongly inhibited." (PMID 32792856, 2020). "As an antagonist of hepatocyte growth factor (HGF), NK4 is a strong suppressor of tumor growth as well as angiogenesis." (PMID 31555593, 2019). "Since hepatocyte growth factor (HGF) is the natural ligand for c-MET receptor and also an important growth factor that has been previously reported to induce tumor growth and drug resistance in cancer cells, we performed HGF measurements in PSC media." (PMID 31072019, 2019). "Recent publications have highlighted hepatocyte growth factor (HGF) and its cognate receptor c-Met as promising therapeutic targets of metastatic tumor growth and osteolysis of bone metastasis." (PMID 30658428, 2019). "Several signaling pathways, including TGF-β, Wnt/β-catenin, Notch, FGF (Fibroblast growth factor), EGF (Epidermal growth factor), and HGF (Hepatocyte growth factor), as well as hypoxia can induce EMT in tumor progression." (PMID 31399111, 2019). "We then investigated if exogenous HGF confers HCC resistance to sorafenib by performing proliferation and colony formation assays through incubation of tumour cells with 50 ng/ml recombinant human HGF." (PMID 31130723, 2019). "Foretinib is a small-molecule kinase inhibitor that inhibits cellular hepatocyte growth factor (HGF)-induced c-MET phosphorylation and prevents HGF-induced response to tumor cells." (PMID 31772236, 2019).
tumor (continued). "The suppressor of cytokine signaling 1 (SOCS1) was recently shown, in HCC lines, to regulate the HGF signal; SOCS1 inhibited the HGF-induced MET-mediated cell growth/proliferation, the invasion of the extracellular matrix, and the dissemination of tumor cells." (PMID 31781608, 2019). "For example, adaptive overexpression of stromal HGF secretion and underexpression of CTLA4, BIM, and antigen presentation genes (B2M, HLA-A, HLA-B, and TAP1) have been cited as mechanisms of tumor resistance upon BRAF inactivation." (PMID 31426419, 2019). "Such a broad spectrum of HGF/c-Met actions led to the investigation of both MET gene expression and c-Met activity in tumor cells." (PMID 30909397, 2019). "In the hypoxic environment, the tumor stroma can increase its secretion of signaling proteins such as tumor necrosis factor-α (TNF-α), TGF-β, PDGF, and hepatocyte growth factor (HGF)." (PMID 31205939, 2019). "It has been demonstrated that MET, induced by tumor inflammatory stimuli, promotes neutrophil migration across endothelium and production of inducible nitric oxide synthase (NOS) after c-met ligand Hepatocyte Growth Factor (HGF) stimulation." (PMID 31799175, 2019). "Once recruited by inflammatory factors within tumor microenvironment, MSCs act as precursors of CAFs which, in turn, contribute to tumor progression by secreting interleukins, chemokines, VEGF, hepatocyte growth factor (HGF), and MMPs." (PMID 30847298, 2019). "There is increasing evidence of the role of the HGF/MET signaling in immune responses, and its potential effects in the immune compartment of the tumor microenvironment." (PMID 31547040, 2019). "We in particular described a double effect of HGF leading to enhanced survival of CLL cells but also driving monocytes/macrophages toward an alternative M2 suppressor phenotype, thus facilitating tumor evasion from immune control." (PMID 30642077, 2019). "They secrete growth factors, hepatocyte growth factor (HGF), FGF and chemokines (CXCL12) that not only stimulate growth and survival of tumor cells, but also induce migration of other cells into the TME." (PMID 30781344, 2019). "The versatile biological effect of HGF in cancer cells is given by its interaction and cooperation with other crucial pathways (MAPK, PI3K/Akt, JAK/STAT) that are considered as drivers of tumor initiation and progression." (PMID 30927908, 2019). "TANs contribute to tumor invasion and angiogenesis through production of matrix metalloproteinases, vascular endothelial growth factor (VEGF), and hepatocyte growth factor (HGF)." (PMID 31455041, 2019). "Lactate functions as the signaling molecule instructing CAFs to secrete HGF, the soluble cue responsible for the induction of MET TKI resistance in tumor cells, as previously reported." (PMID 30927908, 2019). "HGF released from fibroblasts acts as a ligand for a tyrosine kinase receptor, MET, on neighboring tumor cells." (PMID 30631034, 2019). "HGF activates the c-MET signaling pathway, which stimulates the invasive and metastatic potential of various tumor cells." (PMID 31355133, 2019). "HGF, MET-amplification, and EGFR-T790M upregulate PD-L1 expression in NSCLC and promote the immune escape of tumor cells through different mechanisms." (PMID 31747941, 2019). "Furthermore, the study carried out in tumor microenvironment induced drug resistance showed that various BRAF mutated melanoma and ERBB2+ breast cancer cell lines when co-cultured with different fibroblasts affected the sensitivity to vemurafenib and lapatinib, respectively, via HGF/c-MET pathway." (PMID 30680600, 2019). "Stromal cells, integral components of the tumor microenvironment, activate c-MET through HGF release." (PMID 30642077, 2019). "HGF induced activation of MET also triggers AKT or STAT3, induces epithelial–mesenchymal transition (EMT), and promotes multiple pro-tumor effects." (PMID 31367190, 2019).
tumor (continued). "Moreover, because the PD-1/PD-L1 axis promotes tumour cell escape from immune surveillance by inhibiting the proliferation, activation and cytotoxicity of T lymphocytes, we investigated whether HGF-induced upregulation of PD-L1 moderates the proliferation and cytotoxicity of T cells in vitro." (PMID 31747941, 2019). "Hepatocyte growth factor (HGF) is an important fibroblast secreted protein which binds to Met, a specific receptor expressed in tumor cells and actives downstream signal that mediates development and progression of cancers." (PMID 31367190, 2019). "Recent studies have shown that CAFs actively secret cytokines such as HGF, IL6, and SDF-1 which have positive effects on the cancer and the critical roles of TAMs in tumor progression are well documented." (PMID 30894509, 2019). "In some tumor types, cells have been shown to acquire resistance to the cMet inhibitor crizotinib through an FGFR-1-dependent compensatory upregulation of HGF." (PMID 29558956, 2018). "Specifically, N2 type TANs secrete a variety of cytokines, such as CCL2, neutrophil elastase (NE), hepatocyte growth factor (HGF), MMP9, and VEGF, which affect the growth, angiogenesis, invasion and metastasis of the tumor." (PMID 30157906, 2018). "Because the antibodies block the extracellular HGF/MET binding domain, they only inhibit HGF-dependent MET activation and tumor growth." (PMID 30208970, 2018). "Our study found that the increased expression of HGF in CAFs induced by MET-unamplified GC contributed to the malignant phenotype of both MET-unamplified GC and CAFs in tumor microenvironment." (PMID 30158543, 2018). "Cytokines such as HGF, OPN, and stromal-derived factor 1α (SDF-1) secreted in the tumor microenvironment increased CD44v6 expression in CSC and activated the Wnt/β-catenin pathway which promoted migration and metastasis." (PMID 29747682, 2018). "The pro-CSC cytokines, i.e., hepatocyte growth factor (HGF), prostaglandin E2 (PGE2), bone morphogenetic protein (BMP) and interleukins produced by the tumor microenvironment, increase the CSC pool." (PMID 30279970, 2018). "HGF and c-MET usually mediate heterotypic cell–cell interactions, such as epithelial–mesenchymal, including tumor–stroma interactions." (PMID 30513872, 2018). "An overactivation of hepatocyte growth factor (HGF)/mesenchymal-epithelial transition factor (MET) axis promotes tumorigenesis and tumor progression in various cancer types." (PMID 30441809, 2018). "Previous studies have investigated the angiogenic expression profiles in HNSCC tumour tissues compared to normal tissue and have identified VEGF, IL-8/CXCL8, FGF-2 and HGF as key mediators of angiogenesis in HNSCC patients." (PMID 30001714, 2018). "Foretinib (GSK1363089 or XL880), which is an oral multikinase inhibitor developed to primarily target the hepatocyte growth factor (HGF)/Met signaling pathway, has shown anti-tumor effects against some cancers in preclinical and clinical studies." (PMID 29854314, 2018). "An over-activation of the HGF/MET axis promotes tumorigenesis and tumor progression in various cancer types." (PMID 30441809, 2018). "Collectively, these studies demonstrate that HGF and its receptor are strong therapeutic targets for cancer treatment and investigation of factors that govern the influence of HGF/c-Met coupling may lead to novel strategies to combat the metastatic spread of tumours." (PMID 30314527, 2018). "The expansion of MDSCs in the tumor microenvironment is induced by cancer-derived cytokines and growth factors, including IL-6, IL-10, VEGF, hepatocyte growth factor (HGF) or G-CSF, which share ability to induce STAT3 signaling." (PMID 29921770, 2018). "MET overexpression is directly correlated to tumor grade, and likely supports the pro-metastatic role of TME by sensitizing cancer cells to HGF-driven signaling." (PMID 30544501, 2018).
tumor (continued). "HGF/MET autocrine loop activity can lead to the overexpression of Bcl‐2 and mTOR, which inhibit the translation initiation factor eIF2 alpha, making the tumor cells resistant to both autophagy and apoptosis." (PMID 29282893, 2018). "HPA can destroy the integrity of the ECM and BM through the degradation of HSPG, which releases active molecules such as bFGF, HGF, and VEGF anchored in the ECM, thus promoting tumor progression." (PMID 29671088, 2018). "The growth and motility factor Hepatocyte Growth Factor/Scatter Factor (HGF/SF) and its receptor, the product of the MET proto-oncogene, promote invasion and metastasis of tumor cells and have been considered potential targets for cancer therapy." (PMID 28827556, 2017). "Recent studies showed that the dysregulated activation of the HGF/c-Met pathway correlates with the progression of a wide range of human cancers and is thought to contribute to EMT, tumor proliferation, invasion and metastasis." (PMID 28624808, 2017). "Since human HGF activates both human and mouse MET, these animals are vital and fertile, and thanks to the SCID background, they support the growth of human tumor xenotransplants." (PMID 28445144, 2017). "Various studies agree that HGF/MET signaling promotes biological activities, resulting in tumor growth, angiogenesis, and the development of invasive phenotypes, making this receptor an attractive target for potential anticancer treatment." (PMID 28960893, 2017). "Tumor cells were treated with BsAb for 8 h or JNJ for 2 h, and then treated with combinations of HGF and rapamycin (RAPA) for 48 h." (PMID 28404966, 2017). "The expression of platelet‐derived growth factor (PDGF)‐α, PDGF‐β, hepatocyte growth factor (HGF), and GDF‐15 increased in both the primary tumor site group and the micro metastasis group when HCCLM3 cells were cocultured with MSCs." (PMID 28205428, 2017). "To investigate the status of downstream mediators in HGF/c-Met signaling pathway by IRCR201 treatment, we evaluated phosphorylation of Akt and Erk1/2 in PBS- or 15 mg/kg IRCR201-treated MKN45 tumor sections through immunohistochemical analysis." (PMID 28902178, 2017). "Work from our lab demonstrated fibroblasts from normal human ovaries secrete high levels of hepatocyte growth factor, (HGF) which binds to and activate c-MET mediated signaling on EOC tumor cells." (PMID 28060758, 2017). "These two compounds are also able to reduce tumor growth in xenograft and AOM-DSS CRC models by inhibiting pks-harboring E. coli-induced senescence, decreasing hepatocyte growth factor levels and cell proliferation." (PMID 28632155, 2017). "Third, neutralization of HGF by ficlatuzumab cooperated with metabolic blockade by WZB-117, inhibiting tumor growth and suppressing metastatic dissemination." (PMID 28445144, 2017). "In vitro studies show that HGF stimulation leads to significantly increased IL-8, VEGF, and PDGF expression in HNSCC tumor cells through MEK-dependent activation of EGR-1." (PMID 28441771, 2017). "In conclusion, HCC patients with low hepatocyte growth factor (HGF), low VEGFA, high miR-26a levels or low microvessel density in tumor cells have a better prognosis with longer overall survival and time to recurrence." (PMID 28392501, 2017). "In preclinical studies, it inhibited proliferation of a broad range of tumor cell lines (cell IC50 6.2 nM to 4.3 μM) and inhibited HUVEC growth in response to HGF and VEGF as an in vitro model of angiogenesis." (PMID 29231907, 2017). "In HNSCC, matriptase, the protease required to cleave the pro-HGF form, is also co-expressed with c-Met on the surface of HNSCC tumor epithelial cells enabling enhanced HGF-mediated activation of c-Met and downstream signaling." (PMID 28441771, 2017). "Release of hepatocyte growth factor (HGF) from the surrounding stromal cells to activate MET, the HGF RTK on the tumour cell, has also been described as a resistance mechanism." (PMID 28282860, 2017).
tumor (continued). "TGF-β, FGF, epidermal growth factor (EGF), and HGF induce EMT, tumor proliferation and survival, and resistance to anti-cancer agents." (PMID 27965469, 2017). "More commonly, HGF is present in the tumor microenvironment and activates MET expressed on tumor cells in a paracrine fashion." (PMID 28420162, 2017). "It is well established that over-activated HGF/MET signaling increases invasive growth and metastasis by inducing motility of tumor cells and survival in remote tissue sites." (PMID 28456787, 2017). "Composed of the HGF N-terminal hairpin domain and four kringle domains, the NK4 fragment works by binding to the c-Met receptor and blocking tumor proliferation, invasion, and angiogenesis in gallbladder and pancreatic preclinical models." (PMID 28441771, 2017). "Neutrophils have been reported to promote tumorigenesis and progression by secreting tumor growth factors such as vascular endothelial growth factor (VEGF), hepatocyte growth factor, elastase, and MMP9." (PMID 28498842, 2017). "FAK promotes tumor cell invasion and migration through both kinase-independent and kinase-dependent mechanisms; however, direct interaction of MET with FAK promotes HGF-induced cell motility and invasion in GBM." (PMID 28696366, 2017). "It was demonstrated that VEGF suppresses HGF-dependent MET phosphorylation and tumor cell migration through the formation of a VEGFR2/MET heterocomplex." (PMID 29270405, 2017). "Specifically, TANs secrete MMP2, oncostatin M, and hepatocyte growth factor (HGF), which remodel ECM and subsequently induce tumor invasion and metastasis." (PMID 27965469, 2017). "Both HGF inhibition and c-MET blockade (using the small molecule c-MET inhibitor Compound-A) alone resulted in tumor reduction to a similar extent as that observed with gemcitabine." (PMID 29100344, 2017). "SRI31215 or JNJ38877605 also overcame resistance mediated by HGF-producing fibroblasts, demonstrating that inhibition of HGF/MET signaling prevents tumor-microenvironment-mediated resistance to targeted therapy." (PMID 28420162, 2017). "Fibroblasts also confer resistance to anti-cancer therapy through HGF-induced epithelial mesenchymal transition (EMT) and activation of pro-survival signaling pathways such as ERK and AKT in tumor cells." (PMID 28420162, 2017). "Aberrant HGF/c-Met signaling in HNSCC promotes tumor progression and enables the development of distant metastasis by increasing the invasive capacity of HNSCC tumor cells." (PMID 28441771, 2017). "Using an orthotopic model of PC we have shown that “triple therapy” (inhibition of both HGF and c-MET combined with gemcitabine) resulted in the greatest reduction in tumor volume compared to each of the treatments alone or in dual combinations." (PMID 29100344, 2017). "The activity of matriptase, HGFA and hepsin is controlled by the endogenous inhibitors of pro-HGF activation, the HGFA inhibitors (HAI)-1/2, whose expression is reduced in tumor tissues." (PMID 28420162, 2017). "Comparison of plasma and tumor HGF levels from the systemic and local/tumor HGF models revealed the highest plasma HGF levels in the high-dose AAV-HGF animals, whereas the highest tumor HGF levels were found in the Tet-HGF model." (PMID 28147313, 2017). "Some insight into the relative contributions of VEGF and HGF to tumor growth was facilitated by the cross-reactivity of MP0250 as it inhibits human and murine HGF and VEGF with comparable potency." (PMID 29228696, 2017). "In contrast, in the syngeneic RENCA model, MP0250 showed stronger anti-tumor activity than the VEGFR inhibiting kinase inhibitor sorafenib, implicating a more critical role for HGF than VEGF in the growth of these tumors." (PMID 29228696, 2017). "CAFs also secrete factors including VEGF, CXCL12, FGF, IL-8/CXCL8 and PDGF to stimulate tumor angiogenesis, CAFs release factors such as HGF, CCL5 and stanniocalcin 1 (STC1) to stimulate tumor invasiveness and metastasis." (PMID 29383119, 2017).